INS (insulin)
Diseases named in the same sentence as INS in open-access papers (continued):
Sharing a sentence is not in itself a finding about the gene and the disease.
Insulin resistance (continued). "On the other hand, type 2 diabetes (T2D) involves decreased insulin secretion by β-cells, or increased insulin resistance, and represents around 95% of all cases." (PMID 31487953, 2019). "HFD/STZ diabetic rats showed impaired glucose tolerance, reduced insulin secretion, and insulin resistance." (PMID 30915195, 2019). "Due to chronic hyperglycemia, decreasing insulin secretion, as well as up-surging insulin resistance, provides glucose toxicity." (PMID 31337059, 2019). "Specifically, PA has been shown to induce insulin resistance and promote ubiquitination of key insulin signaling molecules such as IRS-1 and Akt." (PMID 31426858, 2019). "We investigated glucagon suppression and its relationship with insulin resistance in prediabetic subjects undergoing atorvastatin therapy; in addition, we studied molecular insulin signaling in pancreatic α-cells exposed to atorvastatin in vitro." (PMID 31546230, 2019). "In adipose tissue, the effect of insulin is to suppress lipolysis and adipose insulin resistance manifests as accelerated lipolysis." (PMID 31474943, 2019). "MS rats had increased systolic blood pressure, triglycerides, insulin levels, insulin resistance index homeostasis model (HOMA), adiponectin, and leptin." (PMID 30987086, 2019). "The HbA1c levels, serum ferritin, hemoglobin (Hb), insulin, Homeostatic Model Assessment of Insulin Resistance (HOMA-IR), C-Reactive Protein (CRP), lipid profiles, and uric acid levels were compared between the groups." (PMID 31372137, 2019). "Recently, insulin-sensitizers such as inositol have been used to improve the insulin resistance in PCOS by regulating autophagy." (PMID 31216618, 2019). "One limitation is the lack of data on the ratio of CSF to serum insulin level which is closely associated with brain insulin resistance, because the influence of insulin resistance on cognitive function is mainly on the brain insulin signaling pathways." (PMID 31440156, 2019). "With CS-treatment, both WT and GPRC6A KO mice developed insulin resistance as assessed by an insulin tolerance test (ITT)." (PMID 30979912, 2019). "Vitamin D supplementation in T2D patients can improve HbA1c, insulin resistance, and insulin in short-term intervention, suggesting that vitamin D can be considered as a therapeutic agent along with the other treatments for T2D." (PMID 30946322, 2019). "In contrast, the global deletion of SMRT leads to the eventual activation Srebp-1c, a lipogenic transcription factor regulated in an insulin dependent manner, which is consistent with the development of insulin resistance." (PMID 31404087, 2019). "In fact, several animal and human studies have supported the view that increased insulin levels, even in the presence of normal weight, induce insulin resistance, by producing insulin receptor desensitization." (PMID 31141900, 2019). "Insulin resistance in adipose tissue, muscle, or the liver places greater demand on insulin secretion from pancreatic beta cells." (PMID 30730811, 2019). "Genes encoding secreted factors such as TNFα and SAA3, that are generally associated with adipose tissue inflammation and insulin resistance, were also upregulated in the gonadal fat of HFD-fed Siah2KO female mice, despite their insulin sensitivity." (PMID 30987673, 2019). "Considering the abnormal response of IUGR, insulin resistance promoted by leucine actually alleviated the drastic changes of serum glucose and insulin concentrations induced by IUGR." (PMID 31847151, 2019). "The IRS‐1 expression, previously decreased upon feeding HFD, increased with Cr complex supplementations, particularly CrHis, indicating the effects of Cr in improving insulin resistance by enhancing insulin signaling." (PMID 30680172, 2019). "Berberine has been shown to be beneficial for HFD-induced insulin resistance, as it improves insulin sensitivity and reduces the homeostasis assessment of the insulin resistance (HOMA-IR) value." (PMID 31118952, 2019).
Insulin resistance (continued). "Initially, in response to the insulin resistance, pancreatic β-cells increase insulin secretion, leading to hyperinsulinemia." (PMID 30759846, 2019). "Insulin resistance results in a failure of insulin-sensitive tissues to respond to the insulin signal." (PMID 30678043, 2019). "In the last few years, there has been significant progress in understanding the processes of insulin action and molecular defects that give rise to insulin resistance." (PMID 31496996, 2019). "The same study also demonstrated that FRB extracts inhibited the expression of tumour necrosis factor-alpha (TNF-α), resulting in an increased insulin sensitivity, reduced insulin resistance and hyperglycaemia." (PMID 31878222, 2019). "NO stimulates the insulin release and the equilibrium between NO and endothelin-1 with a predominium of endothelin-1 inducing insulin resistance." (PMID 31191339, 2019). "Plant-based diets, containing phenolic compounds, have been shown to exhibit remedial benefits by ameliorating insulin secretion and insulin resistance." (PMID 31878222, 2019). "It has been reported that cortisol-induced insulin resistance is due to a decrease in both hepatic and extrahepatic sensitivity to insulin which can be explained on the basis of post-receptor defect." (PMID 31396037, 2019). "Insulin sensitivity was evaluated by euglycemic hyperinsulinemic clamp and homeostatic model assessment insulin resistance (HOMA-IR)." (PMID 31447781, 2019). "This, although striking, is to be expected, taking into account the well-reported glucose-lowering effect of metformin in T2DM European adult populations and the improvement of insulin status in patients with hyperinsulinemia or insulin resistance." (PMID 31527397, 2019). "This condition resembles Type 2 DM (T2DM) in humans, with affected animals developing insulin resistance and failure of pancreatic β-cells to increase insulin production to maintain euglycemia." (PMID 31533709, 2019). "Here, we examined the genome-wide DNA methylation states of monocytes in HIV-infected individuals (n = 37) with varying levels of insulin sensitivity measured by the homeostatic model assessment of insulin resistance (HOMA-IR)." (PMID 31253200, 2019). "Pax8 +/- mice displayed severe insulin resistance, as determined by increased AUC during the insulin tolerance test (ITT)." (PMID 31518338, 2019). "Insulin resistance is defined as the inability of a cell to maintain glucose homeostasis, respond to the physiological level of insulin, and is a characteristic condition of the early state of T2D." (PMID 31635166, 2019). "In insulin resistance state, insulin signaling is impaired, which results in decreased capacity of insulin to stimulate the translocation of GLUT4, whereas the GLUT4 protein content is unchanged." (PMID 29955954, 2019). "IAA improves insulin sensitivity as calculated by the homeostasis model assessment of insulin resistance (HOMA-IR) (p < 0.05), compared with the HFD + vehicle treated group." (PMID 31484323, 2019). "HOMA-β and HOMA-IR, which are based on fasting blood glucose and insulin levels and measure pancreatic beta cell function and insulin resistance, respectively, were calculated." (PMID 30768595, 2019). "In conclusion, we have demonstrated that, in addition to reduced pancreatic insulin secretion, long-term pravastatin treatment induces insulin resistance and muscle wasting." (PMID 31455371, 2019). "This insulin signaling paradox, or so-called selective insulin resistance, explains the classic triad of type 2 diabetes, namely, hyperinsulinemia, hyperglycemia and hypertriglyceridemia." (PMID 31010049, 2019). "Lipid phosphatase Src homology 2 domain-containing inositol-5-phosphatase 2 (SHIP2) is upregulated in diabetic rodent models and suppresses insulin signaling by reducing Akt activation, leading to insulin resistance and diminished glucose uptake." (PMID 30321069, 2019).
Insulin resistance (continued). "In contrast to the more severe whole-body insulin resistance in the corticosterone-treated male mice, the high blood insulin concentrations upon corticosterone treatment resulted in lower glucose production in male mice but not in female mice." (PMID 31265057, 2019). "With fewer functional β-cells secreting insulin in the context of severe insulin resistance, an inability to properly maintain glucose homeostasis ensues, manifesting as T2DM." (PMID 31258514, 2019). "T2DM develops when insulin resistance increases in insulin-target organs, followed by impaired insulin secretion and reduced β-cell mass." (PMID 31121855, 2019). "With pterostilbene administration, a reduction in insulin concentrations (consequently in the Homeostatic Model Assessment for Insulin Resistance (HOMA-IR)) and hepatic triacylglycerol content were observed." (PMID 31035507, 2019). "This sexual dimorphism in terms of energy expenditure causes sex-dependent regulation of insulin action with Cc2−/− females developing insulin resistance and Cc2−/− males developing insulin sensitivity until about 8-9 months of age." (PMID 31266142, 2019). "In the comparison between equally obese insulin sensitive and insulin resistance individuals, phospholipid metabolites including choline, glycerophosphoethanolamine and glycerophosphorylcholine (GPC) were significantly altered." (PMID 31640727, 2019). "Considering the contribution of muscle in glucose uptake in response to insulin, muscles play a major role in the establishment of peripheral insulin resistance." (PMID 30678043, 2019). "After 6 months of HFD feeding, 9-month-old Irs2−/−;A7-Tg mice exhibited increases in plasma insulin levels and insulin resistance, indicating the HFD-induced aggravation of metabolic abnormalities." (PMID 30975165, 2019). "Recent studies indicated associations of central obesity-associated variants in MSRA with metabolic traits, lower fasting levels of serum insulin, and decreased homeostatic model assessment-insulin resistance among men." (PMID 31031707, 2019). "Impairment in glucose use and higher fasting insulin level during insulin resistance status will result in heart failure due to energy starvation." (PMID 30862906, 2019). "In type II diabetes, “insulin resistance” hyperglycemia is the result of inadequate production of insulin and the inability of the body to respond fully to insulin." (PMID 31266160, 2019). "Insulin resistance is characterized by the reduced ability of insulin to stimulate tissue uptake and insufficient glucose absorption, resulting in impaired glucose homeostasis." (PMID 30593599, 2019). "The biological mechanism linking the majority of these lifestyle factors to type 2 diabetes primarily involves promotion of insulin resistance or beneficial effects on insulin sensitivity." (PMID 30971952, 2019). "Type 2 diabetes (T2D) is predominantly characterized by insulin resistance, a state in which the dynamics of insulin signaling and secretion are greatly hindered." (PMID 31426858, 2019). "The development of insulin resistance necessitates a compensatory increase in insulin secretion for the maintenance of glucose levels, and type 2 diabetes develops when insulin secretion becomes insufficient to overcome the degree of insulin resistance." (PMID 31451866, 2019). "DS-EA treatment significantly ameliorated blood glucose, insulin, the homeostasis model assessment of insulin resistance (HOMA-IR) index, and HbA1c in diabetic mice." (PMID 30841605, 2019). "Insulin resistance, a feature of type 2 diabetes, is characterized by reduced activity of insulin despite increased insulin concentrations." (PMID 31699096, 2019). "Insulin resistance (IR) is a metabolic state where insulin-dependent tissues become less sensitive to the actions of insulin, leading to an imbalance in metabolism." (PMID 31273286, 2019).
Insulin resistance (continued). "Insulin resistance and plasma insulin level are known to be higher during the Ramadan fast, especially in the evening and around iftar period." (PMID 31137899, 2019). "The pathophysiology of T2D is characterized by declining β-cell function, impaired glucose metabolism in the liver, and peripheral insulin resistance, a state in which insulin-responsive tissues exhibit reduced responsiveness to normal insulin concentrations." (PMID 30944826, 2019). "These functional defects can have critical metabolic consequences in glucose homeostasis and lead to reduced cellular responsiveness to insulin action, thereby resulting in a condition known as insulin resistance." (PMID 31551782, 2019). "A recent report also indicated that isothiocyanate-rich Moringa oleifera extract reduced weight gain, insulin resistance, and hepatic gluconeogenesis in mice by reducing plasma insulin, leptin and resistin." (PMID 31220177, 2019). "Insulin resistance increases serum levels of free fatty acid, and elevated insulin concentration facilitates free fatty acid flux into hepatocytes and hepatic lipogenesis." (PMID 31788011, 2019). "Short-term supraphysiological estrogen administration can adversely affect glucose tolerance, resulting from the suppression of first-phase insulin secretion and increased insulin resistance." (PMID 30790128, 2019). "Chronic inflammation leads to an impairment of insulin signaling, thereby contributing to the development of hepatic insulin resistance and the progression of NAFLD." (PMID 31215394, 2019). "T2D is characterized by impaired glucose homeostasis with insulin resistance and β-cell dysfunction, the primary trait induced by obesity being insulin resistance in metabolic tissues (adipose, hepatic, and muscular tissues)." (PMID 31141900, 2019). "In the present study, insulin resistance was defined based on cutoff of clamp-derived insulin sensitivity index (lower than the 10th percentile) derived from the normal-weight group." (PMID 30908521, 2019). "The main clinical characteristics of T2D involve systematic insulin resistance and relative insufficiency of insulin secretion." (PMID 31885810, 2019). "Insulin resistance is a pathological condition characterized by the inability of insulin to elicit a hormone response in insulin-dependent cells to regulate glucose and lipid metabolism." (PMID 31035653, 2019). "Insulin resistance, the main contributor of T2D and obesity results from that fact that although there is high levels of insulin present in the circulation, the response to this is defective and brain is not an exception to this." (PMID 31143098, 2019). "Oxidative stress impacts progressive disorders and is linked to metabolic disorders such as T2DM, since the activation of stress pathways plays a key role in the development of the insulin resistance and impaired insulin secretion." (PMID 31010169, 2019). "In the context of cell signaling, it is important to note that a number of insulin signaling intermediates undergo O-GlcNAcylation, which plays a role in insulin resistance." (PMID 31118075, 2019). "In adipose tissue and skeletal muscle, rutin has been shown to increase expression of PPARγ, which further improve insulin resistance, affect insulin sensitivity, and improve glucose uptake." (PMID 30800211, 2019). "It is well known that surgery induces insulin resistance, which impairs the effects of insulin on protein and fatty metabolism." (PMID 31092210, 2019). "Blood glucose, fasting insulin levels, insulin resistance index, and 24-h urinary albumin excretion (UAE) were measured." (PMID 31338070, 2019). "Adiposity and inflammatory cytokines interfere with the normal metabolism, disrupt insulin signaling, thereby contributing to insulin resistance." (PMID 31151163, 2019). "“Insulin resistance” is a chronic state of reduced sensitivity to the effects of circulating insulin." (PMID 30695023, 2019).
Insulin resistance (continued). "Postprandial hyperglycemia results from insulin resistance in muscle, impaired suppression of hepatic glucose production, and decreased insulin secretion." (PMID 31470605, 2019). "Inflammation in NAFLD is one of the main causes of insulin resistance with inflammatory markers such as TNF-α and IL-6 suppressing insulin receptor signaling, thus blocking the action of insulin in hepatocytes." (PMID 30764536, 2019). "Simultaneous treatment with sodium salicylate fully inhibited vascular inflammation, prevented microvascular insulin resistance and significantly improved muscle metabolic responses to insulin." (PMID 30699907, 2019). "Therefore, as recently reviewed, regulating mitochondrial respiration to increase hepatic energy expenditure, along with improving insulin sensitivity, could be an effective strategy to curb complications associated with the metabolic syndrome, including insulin resistance." (PMID 31048842, 2019). "SecinH3 was firstly developed to analyze the harmful effects that insulin resistance generates in human cells, since Arf6 down-regulation hinders insulin response in hepatic cells and impairs glucose-stimulated insulin secretion in pancreatic β cells." (PMID 30884855, 2019). "Thereby, the decline of insulin capability to elevate the uptake of glucose by adipose tissue, liver, and muscle, contributes to the development of insulin resistance." (PMID 30959886, 2019). "Free fatty acid receptor 1 (FFA1) has been recognized to mediate insulin secretion, and pioglitazone has direct effects on glucose-stimulated insulin secretion in addition to the reversion of insulin resistance." (PMID 30863781, 2019). "Our results corroborate that there are complex feedback mechanisms and interplay between the studied anabolic hormones that play an important role in the regulation of glucose metabolism, development of insulin resistance, and modulating insulin sensitivity." (PMID 31080828, 2019). "In the periphery, glucocorticoids counteract insulin action by inducing insulin resistance through reduction of insulin downstream signaling substrates as well as indirectly by increasing lipolysis and proteolysis." (PMID 31133864, 2019). "The insulin resistance index was calculated by the HOMA-IR equation using the level of fasting insulin (μIU/mL) and fasting glucose (mmol/L)." (PMID 31881657, 2019). "The endothelial dysfunction, by decreased flow in insulin-sensitive tissues, aggravates insulin resistance which, in turn, further advances the endothelial dysfunction." (PMID 31885899, 2019). "Insulin resistance is characterized by a reduction in the responsiveness of target tissues to the normal circulating levels of insulin." (PMID 31881654, 2019). "We studied the effects of RES on insulin resistance, glucose homeostasis, and concomitant effects on adipose tissue metabolism and fecal microbiota in insulin-resistant subjects with the MetS." (PMID 30873501, 2019). "Insulin secretory defect accompanied by peripheral insulin resistance is an important characteristic of GDM." (PMID 31808503, 2019). "The relationship between HDL and glucose homeostasis is mediated by several different mechanisms, including HDL’s ability to stimulate insulin secretion by pancreatic beta cells, improving insulin resistance, and regulating lipid metabolism." (PMID 31323735, 2019). "Treatments to alleviate brain insulin resistance, such as intranasal insulin administration, have been evaluated in mice models and AD patients." (PMID 31293498, 2019). "It should be noted that cows that lost BCS postpartum had higher insulin levels, which is a key adaptive mechanism that raises a concern for the development of insulin resistance and changes in insulin responsiveness." (PMID 31861177, 2019).